ZNF146 (zinc finger protein 146)
Synonyms: OZF
Tractability: PROTAC: UniProt records ubiquitination sites on it; ubiquitination databases record sites on it; its protein half-life has been measured.
Gene: Protein-coding gene on chromosome 19 (36,214,602 to 36,238,774, forward strand). Ensembl gene ENSG00000167635.
Subcellular location: Nucleus
Subcellular location (Human Protein Atlas): Nucleoli
Gene Ontology:
Molecular function: protein binding; DNA binding; DNA-binding transcription factor activity, RNA polymerase II-specific; heparin binding; RNA polymerase II cis-regulatory region sequence-specific DNA binding; zinc ion binding
Biological process: regulation of DNA-templated transcription; regulation of transcription by RNA polymerase II
Cellular component: nucleolus; nucleus; nuclear lumen
Genetic constraint (gnomAD): Loss-of-function variants: 9 observed, 22.28 expected, observed/expected ratio (o/e) 0.4, 90% interval 0.24 to 0.7. The upper end of that interval is the gene's LOEUF score, 0.7, which puts it in group 2 of 6, group 1 being the genes least tolerant of losing a copy. Missense variants: 187 observed, 355.45 expected, observed/expected ratio (o/e) 0.53, 90% interval 0.47 to 0.59. Synonymous variants: 105 observed, 123.5 expected, observed/expected ratio (o/e) 0.85, 90% interval 0.73 to 1.
Homologues: Orthologues: chimpanzee ZNF146 (100% identical), macaque ZNF146 (100% identical), dog ZNF146 (99% identical), pig ZNF146 (99% identical), rabbit ZNF146 (98% identical), rat Zfp146 (98% identical), mouse Zfp146 (96% identical), guinea pig ZNF146 (95% identical), rat LOC120095168 (90% identical). Paralogues in human: ZNF260 (80% identical), ZNF568 (59% identical), ZNF182 (59% identical), ZNF658 (58% identical), ZNF16 (57% identical), ZNF250 (57% identical), ZNF484 (57% identical), ZNF300 (57% identical), ZNF33A (56% identical), ZNF33B (56% identical), ZNF717 (56% identical), ZNF543 (55% identical), and 164 more.
Diseases named in the same sentence as ZNF146 in open-access papers:
ZNF146 is named in the same sentence as 12 diseases in open-access papers, as found by Europe PMC text mining. Sharing a sentence is not in itself a finding about the gene and the disease. The quoted sentences say what the papers report.
gastric cancer (5 papers, 2020 to 2023). A primary or metastatic malignant neoplasm involving the stomach. "It has been reported that circPIP5K1A contributes to progression of gastric cancer by miR-376c-3p/ZNF146 signaling." (PMID 34774083, 2021). "In addition, ZNF146 was overexpressed in gastric cancer tissues and regulated the progression of gastric cancer through the CircPIP5K1A." (PMID 37762228, 2023). "CircRNA Phosphatidylinositol-4-Phosphate 5-Kinase Type 1 Alpha (circ_PIP5K1A, hsa_circ_0014130) contributed to the malignant progression of colon cancer via sponging miR-1273a and promoted the developing process of gastric cancer by the miR-376c-3p/zinc finger protein 146 (ZNF146) network." (PMID 34537072, 2021). "ZNF146 was reported to be targeting to distinct sites within LINE-1 sequences at thousands of locations in the genome and to promote tumorigenesis of HCC, gastric cancer, and colorectal cancer." (PMID 37335919, 2023).
colorectal cancer (3 papers, 2022 to 2023). A primary or metastatic malignant neoplasm that affects the colon or rectum. "ZNF146 expression occurs early in the progression of colorectal cancer and is a target of the oncogene c-Myc." (PMID 37762228, 2023). "In fact, similar to our discovery, ZNF146 upregulation has been well-documented in hepatocellular carcinoma and colorectal cancer." (PMID 37762228, 2023). "In addition, ZNF146 was observed to be the downstream target of the LncRNA KCNQ1OT1, and it promoted the development of colorectal cancer." (PMID 37762228, 2023).
heart failure (1 paper, 2023). Inability of the heart to pump blood at an adequate rate to meet tissue metabolic requirements. "ZNF146 and Zfp3 are potential genetic contributors for incident heart failure with reduced ejection fraction." (PMID 37221368, 2023).
lung adenocarcinoma (1 paper, 2023). A carcinoma that arises from the lung and is characterized by the presence of malignant glandular epithelial cells. "The results showed that mRNA and protein levels of ZNF146 were highly expressed in lung adenocarcinoma." (PMID 37762228, 2023).
Lynch syndrome (1 paper, 2024). An autosomal dominant hereditary neoplastic syndrome characterized by the development of colorectal carcinoma and a high risk of developing endometrial carcinoma, gastric carcinoma, ovarian carcinoma, renal pelvis carcinoma, and small intestinal carcinoma. "The gene ontologies for list 7- linked CHTOP, ADNP, HLTF, WAPL, ZMYM4, and ZNF146 to Lynch Syndrome." (PMID 39480826, 2024).
ovarian carcinoma (1 paper, 2025). A malignant neoplasm originating from the surface ovarian epithelium. "ZNF146 can regulate cell cycle progression in human ovarian cancer cells." (PMID 40149467, 2025).
squamous cell carcinoma (1 paper, 2020). A carcinoma arising from squamous epithelial cells. "A previous study showed that ZNF185 silencing strongly impaired keratinocyte differentiation in the head and neck, and in cervical and squamous cell carcinomas, however, functions for ZNF146 have remained unclear to date." (PMID 32849815, 2020).
cancer (7 papers, 2014 to 2025). A tumor composed of atypical neoplastic, often pleomorphic cells that invade other tissues. "Among these DNB factors, ZNF146 is associated with a poor cancer prognosis and functions as a pro-proliferative and growth-sustaining transcriptional regulator in cells, exerting an obvious effect on cellular dynamics." (PMID 40729372, 2025). "Several years ago ZNF146 was shown to be overexpressed in various cancers, though the contribution or molecular mechanisms related to ZNF146/OZF in oncogenic transformation remains opaque." (PMID 35100360, 2022). "Though ZNF146 has been involved in the tumorigenesis of malignant tumors, the knowledge of it function in GC remains extremely limited." (PMID 32190005, 2020). "Overexpression of several of these genes has been previously identified in various cancer types: Slc25a36 (cervical) and Znf146 (colorectal and pancreas)." (PMID 25474466, 2014). "ZNF146/OZF was previously identified as being overexpressed in certain cancers." (PMID 35100360, 2022). "Furthermore, an analysis of the relationship between infiltration estimation and gene expression in gene modules revealed that T-cell CD4+ Th1 in genes ERRFI1, ZBED5, UQCRC2, ZNF146, ABHD17A, YWHAZ, and especially PLSCR4 showed a negative correlation in nearly 40 types of cancer." (PMID 38464509, 2024).
Tumor (6 papers, 2009 to 2025). "For example, circular RNA cESRP1 acts as a tumor promoter in GC by inhibiting miR-376c-3p to upregulate zinc finger protein 146 (ZNF146) expression." (PMID 33472586, 2021). "Within the gene set selected by the GA inthe normal tissue dataset, a combination of higher expression of the genePRELP and a lower expression of the genesUBE4A, ZNF146 in the normal cells waspredictive of tumour capsular penetration." (PMID 21479216, 2011). "Tumor specimens exhibited elevated expression of DTX2, SALL1, ZNF93, ZNF146 and ZSCAN16, contrasting with reduced levels of EGR2, GATA2, and ZEB2." (PMID 40647501, 2025).
ZNF146 also shares sentences with these, for which no sentence is quoted: colon cancer (1 paper); hepatocellular carcinoma (1); melanoma (1).